TREM2 (triggering receptor expressed on myeloid cells 2)
Diseases named in the same sentence as TREM2 in open-access papers (continued):
Sharing a sentence is not in itself a finding about the gene and the disease.
frontotemporal dementia (continued). "Additionally, associations have been found between TREM2 mutations and other neurodegenerative diseases, such as frontotemporal dementia (FTD), Parkinson’s disease (PD), and Nasu–Hakola disease (NHD)." (PMID 40806186, 2025). "For instance, mutations in the TREM2 gene, predominantly expressed on microglia, are associated with several neurodegenerative disorders, including Nasu-Hakola disease, frontotemporal dementia (FTD), and AD." (PMID 39300451, 2024). "Of note, the R47H variant of TREM2 is one of the strongest single allele genetic risk factors for AD, Parkinson's disease, amyotrophic lateral sclerosis (ALS), and frontotemporal dementia (FTD)." (PMID 34135852, 2021). "Moreover, homozygous Trem2 variants have been proposed to be causal for Frontotemporal Dementia (FTD) or linked to increased FTD risk." (PMID 33679762, 2021). "Dysfunctional microglia in frontotemporal dementia (FTD) mouse model might be due to homozygous TREM2 missense mutations such as p.T66M." (PMID 32842621, 2020). "A missense mutation in the gene expressing triggering receptor expressed on myeloid cells 2 (TREM2) was found to be a significant risk factor not only for AD but for frontotemporal dementia and PD as well." (PMID 31507418, 2019). "The TREM2 R47H variant associated with AD has also been found to be a risk factor for PD and frontotemporal dementia (FTD), suggesting a common role for TREM2 dysfunction in multiple neurodegenerative diseases." (PMID 31040847, 2019). "Studies in families with frontotemporal dementia (FTD) or frontotemporal lobar dementia (FTLD) found that PLOSL-associated TREM2 variants T66 M, W198X, Q33X and Y38C in either homozygosity or heterozygosity could also cause FTD." (PMID 28768545, 2017). "Several studies suggest that TREM2-p.R47H could also be a risk factor for Parkinson’s disease, frontotemporal dementia (FTD), and amyotrophic lateral sclerosis." (PMID 25886450, 2015). "Whole‐exome sequencing identified novel homozygous variants in POLH c.638C>G (p.Ser213*) and TREM2 c.154C>T (p.Arg52Cys), classifying the patient as XPV and suggesting that her frontotemporal dementia phenotype could be related to the variant in TREM2." (PMID 32935933, 2020). "TREM-2 alterations, mainly due to TREM-2 mutations causing a loss-of-function, are also related to a variety of neurodegenerative diseases, including AD, PD, MS, Frontotemporal Dementia (FTD), and Amyotrophic Lateral Sclerosis (ALS)." (PMID 31546668, 2019). "TREM2 mutations have been also detected in patients with frontotemporal dementia, who do not have overt bone abnormalities." (PMID 29720600, 2018). "Likewise, a mutation in the Triggering receptor expressed on myeloid cells 2 (TREM2) gene was found to double the risk of AD in two independent case/control samples, associated in a family with frontotemporal lobar degeneration." (PMID 26949549, 2016). "Interestingly, some deleterious biallelic TREM2 variants lead to frontotemporal dementia without bone involvement." (PMID 40301889, 2025). "Genetic variants in TREM2 constitute established risk factors for multiple neurodegenerative diseases, including AD, PD, ALS, and frontotemporal dementia (FTD)." (PMID 40940798, 2025). "This may indicate that TREM2‐stimulating therapeutic approaches could be employed in a variety of different clinical syndromes including AD, frontotemporal lobar degeneration, amyotrophic lateral sclerosis, retinal degeneration, multiple sclerosis, and obesity‐associated metabolic syndromes." (PMID 32154671, 2020). "Rare biallelic mutations that result in loss of function of TREM2 cause Nasu–Hakola disease (NHD) and in some cases Frontotemporal dementia (FTD)." (PMID 30587772, 2018). "The triggering receptor expressed on myeloid cells 2 (TREM2) variant (p.R47H, rs75932628) increases the risk of AD), but not of frontotemporal lobar degeneration (FTLD) in ALS and PD." (PMID 30551598, 2018).
frontotemporal dementia (continued). "While the role of TREM2 in phagocytosis may have important implications for Aβ clearance in AD, the R47H variant has also been implicated in Parkinson’s disease and frontotemporal dementia (FTD), neither of which centrally involves amyloid." (PMID 26438529, 2015).
Obesity (76 papers, 2016 to 2026). Accumulation of substantial excess body fat. "In this study, we aimed to elucidate the molecular mechanisms underlying TREM2 dysfunction in obesity, with a particular focus on the role of pyroptotic adipocyte death and ADAM-mediated TREM2 shedding." (PMID 41509917, 2026). "Consistently, in both obese mice and patients with obesity, the accumulation of TREM2-positive, LAMs has been linked to impaired clearance of dead adipocytes and the progression of insulin resistance and metabolic dysfunction." (PMID 41509917, 2026). "In obesity, lipid-associated macrophages (LAMs)—located in close proximity to hypertrophied adipocytes—exhibit TREM2-mediated regulation of the expression of genes related to phagocytosis, lipid catabolism, and energy metabolism." (PMID 41300781, 2025). "Reduces obesity-associated Trem2+ macrophages and modifies immunometabolic signaling in high-fat diet models." (PMID 40880650, 2025). "Their work demonstrated that TREM2 is selectively expressed in lipid-associated macrophages and was reproducibly validated across both murine and human datasets, implicating it in obesity-induced immune dysfunction." (PMID 41374408, 2025). "Subcluster 0 is the only subcluster with high expression of TREM2, previously defined as lipid-associated macrophages in other diseases, such as obesity and atherosclerosis." (PMID 39867899, 2024). "In obesity, inefficient clearance of dying or dead adipocytes by adipose tissue macrophages leads to the accumulation of dead adipocytes surrounded by TREM2+ lipid-associated macrophages, contributing to insulin resistance and metabolic abnormalities." (PMID 38555350, 2024). "Application of scRNA-Seq in adipose tissue depicted the heterogeneity of ATMs, revealing the lipid-handling Tim4+ and obesity-associated Trem2+ population in mice and tissue immune cell dynamics across lineages in lean and obese humans." (PMID 36875144, 2023). "Using single-cell RNA sequencing, one study identified a subset of TREM2+ lipid-associated macrophages (LAMs) that prominently arise under obesity condition both in humans and mice." (PMID 36119080, 2022). "In the periphery, TREM2 is associated with the occurrence and progression of obesity and its complications, such as hypercholesterolemia, atherosclerosis, and nonalcoholic fatty liver disease (NAFLD)." (PMID 35658903, 2022). "In fact, these lipid-associated macrophages (LAMs) formed CLS for lipid transfer into the macrophages in order to prevent adipocyte hypertrophy and loss of systemic lipid homeostasis under obesity conditions, a process that was dependent on Trem2 expression." (PMID 35480482, 2022). "In adipose tissue in mice, TREM2 was expressed on mature adipocyte and promoted adipogenesis which caused high-fat diet-induced obesity and insulin resistance, whereas another study reported a protective effect of TREM2 on insulin resistance." (PMID 35592778, 2022). "Trem2 deficiency in diet-induced obesity in mice was recently shown to eliminate CLS and infiltrating CD11c+ macrophages and to worsen insulin resistance." (PMID 34990410, 2022). "This program was revealed to be under the control of Trem2 and necessary to counteract obesity-related metabolic disorders, as Trem2 deficiency enhanced HFD-induced weight gain, hypercholesterolemia, glucose intolerance and IR." (PMID 32752107, 2020). "To clarify the role of TREM2 deficiency on obesity-induced insulin resistance, we fed TREM2−/− mice and their WT counterparts with CFD or HFD for 12 weeks." (PMID 31477129, 2019). "Furthermore, TREM2 is crucial for the formation and function of lipid-associated macrophages (LAMs), which play crucial roles in metabolic diseases such as obesity." (PMID 39405126, 2024).
Obesity (continued). "In this report, we delineate the intestinal and brain functions of Jak3 and demonstrate how Jak3 deficiency not only affects obesity-associated gut dysbiosis but also the cognitive functions through microglial regulation of TREM2-medited activation and accumulation of Abeta and pTau in the brain." (PMID 36145091, 2022). "Given that dietary factors alone caused an increase in TREM2+ cells, treatments that target TREM2 may be a viable option for obesity- or diet-induced cognitive decline." (PMID 26888450, 2016). "Additionally, TREM2 signaling is essential for the formation of the lipid-associated macrophages (LAMs) phenotype in obese adipose tissue and regulates the metabolic syndrome in obesity." (PMID 39113887, 2024). "The TREM2-dependent gene program is required to fully differentiate into LAMs and loss of Trem2 aggravates obesity in terms of adipocyte hypertrophy, body fat accumulation and weight gain, although some non-haematopoietic Trem2-dependent effects might contribute to this phenotype." (PMID 39430099, 2024). "Stabilin-1 (STAB1) and triggering receptor expressed on myeloid cell 2 (TREM2) are expressed in a lipid-associated macrophage subset, which supports a tumor immunosuppressive microenvironment and is involved in the progression of obesity and its metabolic complications." (PMID 37033267, 2023). "Trem2 is an important gene which has been implicated to be involved in neurodegenerative diseases and cancer, understanding its role in metabolic diseases and obesity may shed light on additional biological functions of this multifaceted gene." (PMID 36627355, 2023). "Interestingly, a recent study used metabolomics to demonstrate an association between Trem2 deficiency and obesity-induced elevations in serum ceramides and found that Trem2 deficiency exacerbates diet-induced IR in a fat and cholesterol level-independent manner." (PMID 35658903, 2022). "In summary, our findings identify proteolytic cleavage of TREM2 as a key regulatory event driving macrophage dysfunction in adipose tissue during HFD-induced obesity." (PMID 41509917, 2026). "Our findings extend these observations to adipose tissue, demonstrating that ADAM10/17-driven TREM2 cleavage similarly disrupts macrophage function in the context of obesity." (PMID 41509917, 2026). "This study aims to elucidate the functional role of TREM2 cleavage in adipose tissue and explore its potential as a therapeutic target for obesity-related metabolic disorders." (PMID 41509917, 2026). "Here, we find TREM2 is expressed on platelet derived growth factor receptor-α (PDGFR-α) positive ASC in obesity." (PMID 42109717, 2026). "One important question on the obesity-associated ATM accumulation is the obscure relationship between the newly-identified CD9+ and Trem2+ ATM populations and the originally identified ‘M1-like’ CD11c+ ATMs." (PMID 40244655, 2025). "First, we confirmed that the newly identified populations of proinflammatory ATMs (i.e. CD9+ and Trem2+) are induced under HFD-mediated obesity and determined their relationships with the originally identified ‘M1-like’ CD11c+ ATMs." (PMID 40244655, 2025). "For example, scientists have found that Trem2-/- mice exhibit insulin resistance, glucose intolerance, adipocyte hypertrophy, and fat accumulation in diet-induced obesity models." (PMID 40242752, 2025). "First, we confirmed that the newly identified populations of proinflammatory ATMs (i.e., CD9+ and Trem2+) are induced under high fat diet-mediated obesity and determined their relationships with the originally identified “M1-like” CD11c+ ATMs." (PMID 39071288, 2025). "Recent single-cell RNA sequencing analyses have identified a population of TREM2-expressing macrophages, referred to as LAMs, in the white adipose tissue during obesity." (PMID 40636122, 2025).
Obesity (continued). "Although CLS formation has been reported to be positively correlated with M1 macrophages, increased severity of obesity and metabolic syndrome, these studies identify Trem2+ CLSs as a new potential therapeutic target in obesity." (PMID 41287647, 2025). "Following the infiltration into lesions, monocyte-derived cells express CD9, genes involved in cholesterol efflux and lipid handling (Fabp4, Trem2, Abcg1), Lgals3, Gpnmb, Ctsd, and Spp1, which resembles the phenotype of LAMs during obesity." (PMID 39430099, 2024). "TREM2 promotes adipogenesis and diet-induced obesity by upregulating adipogenic regulators and inhibiting the Wnt10b/β-catenin signaling pathway." (PMID 39113887, 2024). "Meanwhile, increased adipogenesis, triglyceride accumulation, and obesity are observed in TREM2 transgenic mice on a high-fat diet." (PMID 39405126, 2024). "Data on the function of LAMs in limiting the obesity phenotype have been contradictory, as genetic deletion of Trem2 improved metabolic health in obese mice, but these effects were not related to the function of Trem2 in immune cells." (PMID 38360943, 2024). "Despite the fact that mice with TREM2 deficiency had fewer LAM macrophages in CLS, they exhibited accelerated obesity with massive adipocyte hypertrophy, insulin resistance, and hyperlipidemia upon HFD feeding." (PMID 37153549, 2023). "TREM2 is involved in the pathogenesis of several diseases, including AD, multiple neurodegenerative diseases, metabolic syndrome-related obesity, fatty liver, and atherosclerosis." (PMID 37563723, 2023). "TREM2 signaling is known to be involved in many different pathologies, including neurodegenerative disease, obesity, and several cancers, where it plays an important role in immunosuppression." (PMID 37791581, 2023). "Several studies have demonstrated that TREM2 protects against neurodegeneration by controlling neuroinflammation closely related to the pathogenesis of AD and obesity." (PMID 36902167, 2023). "Another way to explore the connection between TREM2 and obesity, is to analyze the BMI of people with SNPs in the TREM2 gene." (PMID 36627355, 2023). "Further, we analyzed the expression levels of TREM2, a receptor expressed mainly on microglia and modulated in obesity-induced insulin resistance, a condition in which TREM2 exerts anti-inflammatory and neuroprotective effects." (PMID 36902167, 2023). "In spite of the recent interest in TREM2, there is little epidemiological evidence for involvement of TREM2 in human obesity." (PMID 36627355, 2023). "For instance, TREM2+ macrophages resided in different tissues during obesity, including adipose tissue and liver, with different phenotypes, such as LAMs, non-alcoholic steatohepatitis-associated macrophages, and scar-associated macrophages." (PMID 36814909, 2023). "Recent studies have demonstrated sex differences of infiltrating macrophages in controlling TREM2-dependent lipid homeostasis in obesity." (PMID 37833781, 2023). "Here, a computational study using public databases, brings direct evidence for the involvement of TREM2 in human obesity." (PMID 36627355, 2023). "In mice with HFD-induced obesity, emodin effectively induced the polarization of M2 macrophages through the upregulation of TREM2 expression." (PMID 38053837, 2023). "In white adipose tissue, CD9+TREM2+ macrophages correlated with the severity of inflammation and influenced obesity pathology." (PMID 36814909, 2023). "In Trem2 transgenic mice fed with a high-fat diet, the upregulation of adipogenic regulators was observed, which indicates that Trem2 promotes obesity and adipogenesis." (PMID 36982629, 2023). "The pan-marker CD68, proinflammatory marker iNOS, and novel markers TREM2 and CD9 are widely used markers in macrophages that are strongly associated with obesity and diabetes." (PMID 36814909, 2023).
Obesity (continued). "High-resolution investigations first delineated obesity-associated lipid-laden ATMs with CD9 expression, which were further demarcated by Triggering receptor expressed on myeloid cells 2 (Trem2) expression in both mice and humans." (PMID 36875144, 2023). "Although these researchers did not further identify the specific type of nonhematopoietic cells that protect against IR, it would be interesting to study the exact functions of TREM2 expression in adipose tissue during obesity." (PMID 35658903, 2022). "In the periphery, TREM2 influences lipid metabolism by regulating the onset and progression of obesity and its complications, such as hypercholesterolemia, atherosclerosis, and nonalcoholic fatty liver disease." (PMID 35658903, 2022). "We have discussed the influence of TREM2 on obesity, atherosclerosis and NAFLD, which are considered metabolic comorbidities of AD and disrupt the homeostasis of peripheral lipid metabolism." (PMID 35658903, 2022). "The triggering receptors on microglial cells 2 (TREM2) interact with Jak3 in the brain, and IEC deficiency of Jak3 leads to an impairment of Jak3 interactions with TREM2 in the brain during HFD-induced obesity." (PMID 36145091, 2022). "In fact, TREM2 has been proven to have protective effects in neurodegenerative diseases, fatty liver, obesity, atherosclerosis, and tumour." (PMID 36463233, 2022). "In fact, TREM2 can influence the development of obesity and its complications, such as hypercholesterolemia, atherosclerosis and NAFLD, in several ways, which will be discussed hereafter, including some lipid metabolism-associated mechanisms." (PMID 35658903, 2022). "LAMs are a subset of conserved TREM2 + macrophages that play a protective role in obesity mainly through the formation of crown-like structures in adipose tissue." (PMID 35658903, 2022). "Although the specific role of TREM2 in obesity remains controversial, considering the given evidence, it is more likely that TREM2 serves as a protective factor that prevents the loss of lipid homeostasis." (PMID 35658903, 2022). "In summary, TREM2 can influence obesity and its concomitant phenotypes, such as adipocyte hypertrophy, inflammation and IR." (PMID 35658903, 2022). "TREM2 KO mice exhibit increased obesity, insulin resistance and altered adipose tissue remodeling in response to HFD feeding." (PMID 34122343, 2021). "TREM2 is required for induction of monocyte-derived LAMs, in which LPL and APOE are induced by a TREM2-dependent mechanism as a consequence of HFD-induced obesity in mice." (PMID 34122343, 2021). "They showed that the function of TREM2 is a feedback mechanism to control obesity-induced IR by regulating adipose tissue remodeling pathways." (PMID 32982666, 2020). "Recently, a novel and conserved macrophage named lipid-associated macrophage (LAM) with high levels of the lipid receptor Trem2 has been proven to be the predominantly expanded immune cell subset in adipose tissue in multiple obesity-related mouse models." (PMID 32646451, 2020). "Published studies reported that level of trigger receptor expressed on myeloid cells 2 (TREM2) in adipose tissue is up-regulated in animal models of obesity." (PMID 31477129, 2019). "We first examined obesity, insulin resistance and adipose tissue remodeling in TREM2 knockout (TREM2−/−) and wild-type (WT) mice under HFD challenge." (PMID 31477129, 2019). "Published articles have revealed that in animal models of obesity, TREM2 gene expression was up-regulated in adipose tissue." (PMID 31477129, 2019). "In the present study, we tried to determine the effect of TREM2 gene deficiency on adipose tissue remodeling in mice of high-fat diet (HFD), and explored the effect of TREM2 on obesity-induced insulin resistance." (PMID 31477129, 2019).